MDM2 (MDM2 proto-oncogene)
Diseases named in the same sentence as MDM2 in open-access papers (continued):
Sharing a sentence is not in itself a finding about the gene and the disease.
neuroblastoma (continued). "Finally, we found that Cisplatin and various BH3-mimetics could enhance RG7388-mediated apoptosis in RG7388-resistant neuroblastoma cells, thereby partially overcoming resistance to MDM2 inhibition." (PMID 39222276, 2024). "In addition, MDM2 protein overexpression is often present even in neuroblastomas without MDM2 gene amplification, and is linked to a poorer prognosis of patients." (PMID 33291373, 2020). "Furthermore, the chromosome 12q arm contains other – in neuroblastoma not infrequently amplified – genes, among them oncogenes and cell cycle-associated genes (MDM2, CDK4, OS9, and GLI1)." (PMID 25161957, 2014). "Recently, we have demonstrated that SP141, a small molecule that induces MDM2 degradation and inhibits MYCN protein level, exhibits several beneficial effects in neuroblastoma." (PMID 39802403, 2025). "Elevated MDM2 expression is required for high-level expression of MYCN in small-cell lung cancer, retinoblastoma, neuroblastoma, and medulloblastoma cells." (PMID 39802403, 2025). "Similar to MDM2, which was originally discovered from double minute chromosomes in NIH-3T3 cells, MYCN was also found to form extrachromosomal double minutes in neuroblastomas." (PMID 39802403, 2025).
neuroblastoma (continued). "To further demonstrate the generality of these coordinated dynamics of ecDNA species under selective pressure, we treated the neuroblastoma TR14 cells with nutlin-3a, a targeted inhibitor of MDM2." (PMID 39506152, 2024). "Known neuroblastoma-related genes such as MYCN, TERT, ODC1, CDK4, and MDM2 were recurrently affected by different classes of complex rearrangements including ecDNA, chromothripsis, and CnCs." (PMID 37868040, 2023). "In neuroblastoma, it has been reported that the 3′UTRs of VEGF and MYCN, a homologue of c-Myc, contain AREs that can be bound to, and stabilized by MDM2." (PMID 35326742, 2022). "Pharmacological inhibition of CDK4/6 with ribociclib or abemaciclib decreased proliferation in a broad set of neuroblastoma cell lines, including CDK4/MDM2-amplified, whereas MDM2 inhibition by Nutlin-3a was only effective in p53wild-type cells." (PMID 35859155, 2022). "FMRP has been found to regulate the stability of MDM2 mRNA and the long noncoding RNA TUG1 in mouse neural stem cells and mouse neuroblastoma N2a cells, respectively." (PMID 35534866, 2022). "The present study is the first to report the in vitro and in vivo anti-neuroblastoma effects of SP141, a potent and selective MDM2 inhibitor discovered in our lab." (PMID 33291373, 2020). "The ring domain of MDM2 binds to the MYCN mRNA adenylate/uridylate-rich elements (AREs) within the 3’UTR, and thereby increases the MYCN mRNA stability and translation in neuroblastoma cells." (PMID 33291373, 2020). "Prior studies showed that MYCN can drive MDM2 expression in neuroblastoma cells, which we corroborated in SH-SY5Y neuroblastoma cells with ectopic MYCN overexpression." (PMID 33425720, 2020). "In the present study, we tested a unique MDM2 inhibitor, SP141, for its therapeutic efficacy and safety in neuroblastoma tumor models." (PMID 33291373, 2020).
neuroblastoma (continued). "Among 10 high-MYCN-expressing cell lines examined in this and other studies, including five retinoblastoma, three neuroblastoma, and two SCLC lines, all required high-level MDM2 expression for MYCN expression and viability." (PMID 33425720, 2020). "Several other chemical classes of MDM2 inhibitors have been developed, among which RG7112, RG7388, MI-63, NDD0005 and MI-773 have been demonstrated to suppress neuroblastoma cell viability and proliferation in preclinical models." (PMID 29416773, 2018). "In conclusion, these in vivo data confirm our in vitro findings and strongly support further exploration of combined inhibition of MDM2 and BCL2 in the context of neuroblastoma." (PMID 28915653, 2017). "Sensitivity of the present panel of neuroblastoma cell lines to RG7388 was analysed in relation to their MYCN, p14ARF and MDM2 status." (PMID 25844600, 2015). "A recent report has demonstrated the importance of dual inhibition of Mdm2 and VEGF in neuroblastomas, which subsequently led to slower tumor growth and less vascularization of the tumors." (PMID 24040331, 2013). "Nutlin-3-bound MDM2 was shown to retain several activities, including MDMX E3 ubiquitin ligase activity, but the consequence of this in neuroblastoma are completely unexplored." (PMID 23091802, 2012). "To explore whether alternative targeting of the DNA damage response by inhibiting MDM2 could also be synergistic with KDM6B inhibition, we treated five different neuroblastoma cell lines with the combination of GSK-J4 and Nutlin-3." (PMID 40253363, 2025). "Amplification of MDM2 also occurs in neuroblastoma, and even in the absence of gene amplification, MDM2 protein overexpression is often present and correlates with a poorer prognosis for patients." (PMID 40115016, 2025).
neuroblastoma (continued). "In addition, another MDM2 antagonist in clinical trials, MI-773 (SAR405838), has been shown to potentiate the cytotoxicity of doxorubicin in neuroblastoma cell lines." (PMID 40115016, 2025). "Finally, single-cell Circle-seq confirmed co-enrichment of the MYCN, MDM2 and CDK4 ecDNA species in individual TR14 neuroblastoma cells." (PMID 39506152, 2024). "One study tested a selective MDM2 inhibitor, SP141, for efficacy in neuroblastoma tumor models." (PMID 37835416, 2023). "MDM2 overexpression maintains MYCN stabilization and translation in paediatric neuroblastoma cells and represents an unfavourable prognostic factor of neuroblastoma." (PMID 35655142, 2022). "Here we present detailed biological data of an aggressive neuroblastoma subgroup hallmarked by 12q amplification and atypical clinical presentation for which our in vitro studies indicate that CDK4 and/or MDM2 inhibition also could be beneficial." (PMID 35859155, 2022). "Conversely, MYCN has been shown to induce MDM2 expression in neuroblastoma cells, yet it is unclear if MYC shares this ability, if MYC family proteins upregulate MDM2 in other malignancies, and if this regulation occurs during tumorigenesis as well as in cancer cell lines." (PMID 33425720, 2020). "Overexpression of pVHL30-GFP, and not pVHL19-GFP, in motor neuron-neuroblastoma hybrid MN-1 cells resulted in the pull down of endogenous MDM2." (PMID 32985545, 2020). "Likewise, SP141 has also been found to reduce the protein levels of both MDM2 and MDMX (MDM4) in neuroblastoma cells." (PMID 33291373, 2020).
neuroblastoma (continued). "An increasing number of targeted agents are now entering early phase paediatric trials including the lead Novartis MDM2 antagonist, HDM‐201, as part of the Next Generation Personalised Neuroblastoma Therapy (NEPENTHE) trial (NCT02780128) and the dual MDM2/MDMX inhibitor ALRN‐6924 (NCT03654716)." (PMID 30536898, 2019). "Three known risk factors, the presence of a MYCN amplification in the tumor, patient age > 18 months at diagnosis and stage 4 disease according to the International Neuroblastoma Staging System (INSS), significantly correlated with elevated MDM2 expression in tumors." (PMID 29416773, 2018). "To date, however, none of the MDM2 inhibitors has entered clinical treatment of patients with neuroblastoma." (PMID 29416773, 2018). "Although MDM2 has been validated as a promising target in preclinical models, no MDM2 inhibitors have yet entered clinical trials for neuroblastoma patients." (PMID 29416773, 2018). "Given the improved in vitro efficacy of combined ALK and MDM2 inhibition, we next determined whether ceritinib in combination with CGM097 was effective in the neuroblastoma mouse xenograft models." (PMID 28425916, 2017). "Two recent preclinical studies have shown marked anti-neuroblastoma activity of idasanutlin, a second-generation MDM2 antagonist with superior potency and selectivity that is now prioritized for clinical development." (PMID 28915653, 2017). "MDM2 is a direct target gene of MYCN and non-syntenic co-amplification of MDM2 and MYCN has been reported in neuroblastoma." (PMID 23226679, 2012).